ALB (albumin)
Diseases named in the same sentence as ALB in open-access papers (continued):
Sharing a sentence is not in itself a finding about the gene and the disease.
Hypocalcemia (114 papers, 2012 to 2026). An abnormally decreased calcium concentration in the blood. "Low albumin concentration, which is common in cancer patients, can cause the phenomenon of pseudo-hypocalcemia." (PMID 41601884, 2026). "Early initiation of KRT within one year was associated with younger age, lower serum albumin levels, hypocalcemia, and a more significant decline in total eGFR compared to patients who did not commence dialysis within the same timeframe." (PMID 40142789, 2025). "Thyroid involvement: urinary loss of hormone-binding proteins.Hypocalcemia: decreased albumin level, increased renal tubular reabsorption, abnormalities in vitamin D metabolism." (PMID 40375997, 2025). "The diagnostic approach to hypocalcemia should begin with confirming calcium levels; correcting for albumin; and measuring PTH, phosphate, and serum magnesium." (PMID 40492015, 2025). "What is more noteworthy is that even mild hypocalcemia (≥7.5–<8.5 mg/dl) or hypercalcemia (≥10.3–<12 mg/dl) has predicted to increase 10%–20% risk of 30-day mortality when the albumin-corrected calcium level increases by 1 mg/dl in ICU patients." (PMID 36619536, 2022). "This is mediated through the binding of calcium ions to serum albumin, which causes hypocalcemia, and an increase in the release of calcium ions from the sarcoplasmic reticulum." (PMID 34762357, 2021). "A significant interaction was found between hypocalcemia and DM, serum albumin, and Lp (a) on the risk of first incident AMI." (PMID 33083294, 2020). "This study will also evaluate the sensitivity and specificity of albumin corrected calcaemia as a diagnostic tool for hypocalcaemia (ionised calcaemia as the gold standard) among pregnant women in the Nkongsamba Regional Hospital, Cameroon." (PMID 33152011, 2020). "The main objectives of this study are to describe the blood calcium level (total, albumin corrected, and ionised calcaemia) and associated maternofoetal outcomes while identifying determinants of calcium supplementation and ionised hypocalcaemia." (PMID 33152011, 2020). "Similar associations were observed for hypomagnesemia and hypocalcemia (albumin-corrected calcium) with ORs of 1.25 (95% CI, 1.07–1.45) and 1.22 (95% CI, 1.02–1.46)." (PMID 31022222, 2019). "Hypomagnesemia and hypocalcemia (albumin-corrected) were also associated with readmission, with ORs of 1.25 (95% CI, 1.07–1.45) and 1.22 (95% CI, 1.02–1.46), respectively." (PMID 31022222, 2019). "Compared with those whose serum calcium concentrations were normal, patients with hypocalcaemia tended to be older, with lower blood pressure, lower concentration of serum albumin, higher TIMI risk score for STEMI and higher neutrophil count on admission." (PMID 24926660, 2014). "Four patients discontinued because of grade 2 or 3 toxicity during chemoradiation (fatigue; weight loss, nausea, and anorexia; abnormal liver function; weight loss, low albumin, and hypocalcaemia)." (PMID 22134511, 2012). "Patients with lower potassium, calcium, and/or albumin-corrected calcium levels tended to have longer QTc intervals, consistent with evidence from the general population showing that hypokalemia, hypocalcemia, and hypomagnesemia are established risk factors for arrhythmias." (PMID 41301770, 2025). "Beeswarm plots revealed directional associations, with lower weight, elevated CCI, higher SOFA score, tachycardia, increased respiratory rate, elevated lactate, hypocalcemia, low hematocrit, and leukocytosis all linked to greater mortality risk, whereas higher albumin was protective." (PMID 41149453, 2025). "Vitamin and magnesium deficiencies are known to be associated with low serum albumin levels because they may be accompanied by hypocalcemia." (PMID 39517408, 2024). "Almost 30-55% in the plasma and a decrease in serum albumin will also cause hypocalcemia." (PMID 35611244, 2022).
Hypocalcemia (continued). "Finally, calcium is predominantly bound to albumin in plasma, and a decrease in serum albumin or total protein levels, mainly occurring in the third trimester, will cause hypocalcemia." (PMID 35678023, 2022). "The finding that lower magnesium, sodium and albumin were independently associated with ionized hypocalcemia, with a strong trend for higher phosphate, suggests these biochemical derangements should be specifically considered in the assessment of hypocalcemic patients." (PMID 23734769, 2013). "Low magnesium, sodium and albumin were independently associated with hypocalcemia on admission." (PMID 23734769, 2013). "Serum albumin, magnesium, free calcium, vitamin D, and PTH levels, as well as kidney function, must be assessed to understand the cause of hypocalcemia." (PMID 41601884, 2026). "In the case of low serum PTH or symptoms of hypocalcaemia, subsequent measurements of ionized or albumin-adjusted serum calcium are needed in the postoperative interval (days–weeks) to assess any need for or guide treatment of hypoparathyroidism." (PMID 41229353, 2025). "In patients with hypocalcemia, it is essential to evaluate serum albumin, phosphorus, magnesium, 25(OH) vitamin D, and particularly PTH levels." (PMID 40717880, 2025). "Our findings reveal that a more pronounced decline in eGFR, alongside factors such as younger age, lower serum albumin levels, hypocalcemia, and effective management of electrolyte abnormalities, serves as a robust predictor for early KRT initiation." (PMID 40142789, 2025). "As the primary carrier of Ca, reduced ALB lowers total Ca by decreasing its protein-bound fraction, a phenomenon known as “hypoalbuminemic hypocalcemia”." (PMID 40431588, 2025). "Glycated albumin, measured in the third trimester, emerges as a significant predictor for multiple adverse outcomes, including neonatal hypocalcemia, polycythemia, respiratory disorders, and myocardial hypertrophy." (PMID 39519218, 2024). "When assessed according to the albumin-adjusted serum calcium levels, the incidence of grade ≥ 1 and ≥ 3 hypocalcemia decreased to 35.7% (n = 187) and 2.5% (n = 13), respectively." (PMID 38360579, 2024). "In summary, in women with GDM, glycated albumin is a promising prognostic factor for predicting large-for-date babies, myocardial hypertrophy, as well as neonatal hypoglycemia, hypocalcemia, and polycythemia." (PMID 39519218, 2024). "Not only albumin, calcium ion also varies greatly in the population, such as hypercalcemia defined as calcium concentration higher than 10.5 mg/dl, and hypocalcemia defined as calcium concentration less than 8.5 mg/dl." (PMID 38173765, 2024). "The identification of lymph node metastasis, total thyroid surgery, decreased PTH and 25(OH)D3 levels, and albumin concentration proved to be instrumental in guiding the surgical team toward preventing the onset of hypocalcemia." (PMID 40071247, 2024). "To date, no study has clarified the differences in the frequencies of true hypocalcemia (adjusted for albumin) and unadjusted hypocalcemia." (PMID 38360579, 2024). "The identification of lymph node metastasis, total thyroid surgery, decreased PTH and 25(OH)D3 levels, and albumin concentration are crucial factors in guiding the surgical team to prevent the onset of hypocalcemia." (PMID 40071247, 2024). "Adverse events included hypocalcemia (calcium corrected for albumin less than 8.5 mg/day), renal functional impairment (0.5 mg/dL or more increase in serum creatinine) within 30 days of treatment, or a fever (>38 °C) within 48 hours of drug administration." (PMID 39416429, 2024). "Ten (6.09%) patients had hypocalcemia and two (1.34%) had hypercalcemia corrected to albumin levels." (PMID 38592241, 2024). "Two weeks after denosumab administration, routine biochemical tests revealed severe hypocalcemia (serum calcium 6.2 mg/dl (1.55 mmol/L), with normal serum albumin levels and secondary hyperparathyroidism (PTH 332 pg/ml)." (PMID 39639476, 2024).
Hypocalcemia (continued). "If mild hypocalcemia, defined as serum calcium (adjusted for albumin) between 7.5 and 8.5 mg/dl, accounts for up to 7% of patients treated with denosumab for osteoporosis, the incidence is higher in patients with bone metastases." (PMID 39639476, 2024). "Hypocalcaemia according to the guidelines is defined as an albumin-corrected serum calcium below the lower reference value, ranging from < 2.10 to < 2.20 mmol/L, depending on the assay." (PMID 38308768, 2024). "The incidence of hypocalcemia was lower with albumin-adjusted serum calcium levels than with measured serum calcium levels (without albumin adjustment)." (PMID 38360579, 2024). "In our study, severe hypocalcemia [albumin corrected calcium of <7.5 mg\dl) occurred in 5 patients (2%) after ZOL and in 8 patients (6%) after Dmab treatment (P = .06)]." (PMID 39416429, 2024). "Therefore, the specific mechanisms underlying hypocalcemia may involve vitamin D acting as a steroid hormone in immune regulation, changes in intestinal calcium absorption, decreased serum albumin levels, reduced calcium influx, and decreased parathyroid hormone secretion." (PMID 38145047, 2023). "An albumin-corrected total serum calcium level below 2.2 mmol/L (8.9 mg/dL) was considered as hypocalcemia." (PMID 37371636, 2023). "The diagnosis of primary hypoparathyroidism is supported by the findings of hypocalcemia, which must be corrected for albumin values, and low or undetectable parathormone." (PMID 37568563, 2023). "The two participants with low calcium levels had mild and asymptomatic hypocalcemia (i.e., uncorrected calcium levels of 2.02 mmol/L (albumin 42 g/dL) and 2.14 mmol/L (albumin 44 g/dL)." (PMID 37293490, 2023). "The reduced incidence in this study was probably due to the definition of “true hypocalcemia”, which was calculated after correcting calcium for albumin from the initiation of ICI to their last follow-up." (PMID 36672478, 2023). "Technical limitations related to measurement of ionized calcium make the use of calcium corrected for albumin preferable to diagnose hypocalcemia." (PMID 35407442, 2022). "Based on the albumin-adjusted total Ca levels, we divided all patients into the hypocalcemia and non-hypocalcemia group." (PMID 36698873, 2022). "Patients with hypocalcemia (serum calcium corrected for albumin < 8 mg/dL), in combination with reduced or inappropriately normal parathormone levels, found in at least two tests, have hypoparathyroidism." (PMID 35407442, 2022). "We included 1,954 confirmed patients with ICH and divided them into hypocalcemia and non-hypocalcemia groups according to albumin-adjusted total Ca levels." (PMID 36698873, 2022). "In this study, the prevalence of total crude and albumin-corrected hypocalcaemia were 61.64 [58.69–64.50]% and 56.70 [53.72–59.64]%, respectively." (PMID 35584129, 2022). "The prevalence of total crude and total albumin-corrected hypocalcaemia in this study were 61.64 [58.69–64.50]% and 56.70 [53.72–59.64]%, respectively (p-value = 0.000), while the prevalence of ionised hypocalcaemia was as low as 2.89 [2.04–4.07]%." (PMID 35584129, 2022). "Only 28 participants (2.61 [1.81–3.74]%) had hypocalcaemia when defined using the three methods (ionised, total crude and albumin corrected total calcium) at the same time." (PMID 35584129, 2022). "The prevalence of total crude and total albumin-corrected hypocalcaemia in this study was 61.64 [58.69–64.50]% and 56.70 [53.72–59.64]%, respectively (p-value = 0.000)." (PMID 35584129, 2022). "When compared with the total crude and total albumin-corrected prevalence of hypocalcaemia, this showed statistically significant differences with p-values of 0.000 in each case." (PMID 35584129, 2022). "Serum calcium level was corrected for albumin concentration, and hypocalcaemia was defined as corrected calcium < 2.11 mmol/L." (PMID 34876077, 2021).
Hypocalcemia (continued). "As albumin levels decline due to volume expansion, it is therefore essential to evaluate calcium corrected for albumin or ionized calcium for the assessment of hyper- or hypocalcemia." (PMID 33805460, 2021). "Plasma alkalosis induces the binding of calcium ions to serum albumin molecules, resulting in hypocalcemia." (PMID 34762357, 2021). "Eventually, the infant experienced symptomatic hypocalcaemia (ionized Ca 3.4 mg/dl), likely exacerbated by contemporary infusion of albumin." (PMID 34233724, 2021). "A recent cross-sectional survey evaluating albumin-corrected serum calcium levels in women in late pregnancy reported an alarmingly high prevalence of hypocalcaemia (58%) among women in the Nkongsamba Health District; Cameroon." (PMID 33152011, 2020). "In fact, patients with hidden hypocalcemia had lower BMI and serum albumin levels than patients with apparent hypocalcemia." (PMID 32157180, 2020). "Maternofoetal outcomes associated with hypocalcaemia will be determined as well as the sensitivity and specificity of total and albumin-corrected calcaemia in diagnosing hypocalcaemia." (PMID 33152011, 2020). "True hypocalcemia incidence was calculated after correcting calcium for albumin from the initiation of ICPI to their last follow-up." (PMID 32587615, 2020). "Multivariate predictors of hypocalcemia included a catheter for vascular access, low albumin and high iPTH." (PMID 31848883, 2020). "True hypocalcemia incidence was only 1.02% (n = 1) as most of the hypocalcemia events normalized during the next follow-up or after correcting to albumin." (PMID 32587615, 2020). "Our data suggest that the true hypocalcemia incidence after using albumin-corrected calcium values is very low in patients receiving IPCI, even in the presence of calcium altering factors." (PMID 32587615, 2020). "Our data suggest that the true hypocalcemia incidence after using albumin-corrected calcium values is very low in patients receiving ICPI, even in the presence of calcium altering factors." (PMID 32587615, 2020). "For the sensitivity analysis, of 878 patients (97%) had an albumin-corrected Ca ≥ 2.1 mmol/L value available at cinacalcet initiation, 395 (45%) subsequently developed hypocalcemia (Online Resource 1)." (PMID 31848883, 2020). "The initial laboratory investigation showed elevated parathyroid hormone level (311.2 pg/mL), hypocalcemia (albumin-corrected serum calcium 4.3 mg/dL), hypocalciuria, hyperphosphatemia, hypophosphaturia, and vitamin D deficiency." (PMID 33320452, 2020). "With ionised calcaemia as the gold standard for diagnosis, total calcaemia and albumin-corrected calcaemia in other pathological states have been found to overestimate the burden of hypocalcaemia." (PMID 33152011, 2020). "The recent study in Cameroon (Nkongsamba Regional Hospital) reported an albumin-corrected hypocalcaemia prevalence in pregnancy." (PMID 33152011, 2020). "The perceived burden of hypocalcaemia in pregnancy is significantly different when albumin-corrected values are considered." (PMID 31697767, 2019). "In our study, the median LOS for patients with severe hypocalcemia was 6.5 days when measured as free calcium and 7.5 days when measured as albumin-corrected calcium, respectively." (PMID 31022222, 2019). "The prevalence of albumin-uncorrected and corrected hypocalcaemia (the standard prevalence of hypocalcaemia for our study) in late pregnancy was 85.88 [81.71–89.24]% and 58.76 [53.42–63.90]% respectively." (PMID 31697767, 2019). "Hypocalcemia in these animals was likely due to decreased albumin since calcium is bound to albumin in circulation." (PMID 31106217, 2019). "Our findings reported a crude hypocalcaemia prevalence of 85% which when we corrected measured calcium levels for albumin changes in pregnancy, the prevalence significantly dropped to 59%." (PMID 31697767, 2019).
Hypocalcemia (continued). "Hypocalcaemia in patients with cancer frequently relates to a poor nutritional status, and these individuals often have low albumin and/or vitamin D concentrations; therefore it is important to correct serum calcium measurements for albumin levels." (PMID 30236112, 2018). "In retrospective analyses, conducted before the introduction of bisphosphonate or denosumab treatment, hypocalcaemia was reported in 5–13% of patients with bone metastases, depending on the formula used to correct for albumin levels." (PMID 30236112, 2018). "Only unbound ionized calcium is physiologically active; therefore, serum calcium concentration must be corrected for albumin concentration in order to confirm a diagnosis of hypocalcaemia." (PMID 30236112, 2018). "She had the diagnosis of BA at the age of 2 months, when she presented with hypocalcemia (1.4 mmol/l; albumin-corrected calcium: 1.5 mmol/l; normal range: 2.0–2.8 mmol/l)." (PMID 26800885, 2016). "Hypocalcemia is commonly seen even after correction for low albumin levels, especially when in leakage with resulting dengue haemorrhagic fever." (PMID 25884693, 2015). "It is within the realm of science that hypocalcemia is due to fall in free calcium, albumin-bound calcium or both whilst hypercalcemia is due to the influx of the calcium from the calcium pool into the extracellular fluids is more than its efflux." (PMID 27047206, 2015). "Such chronic diseases that lead to lower serum albumin ensure low calcium level by default contribution to hypocalcemia." (PMID 27047206, 2015). "In the present study, although albumin level seemed to be significantly lower in hypocalcaemia group, all data were within a small zone and the normal range." (PMID 24926660, 2014). "Although reports evaluating the risk of hypocalcemia when using 5% albumin without citrate (i.e., with heparin anticoagulation) as a replacement fluid are limited, a case series reported asymptomatic hypocalcemia during TPE in one of seven pediatric patients." (PMID 41299855, 2025). "In the case of severe or refractory hypocalcemia, we recommend the complementary measurement of serum albumin, ionized-bound calcium, and albumin-bound calcium, magnesium, PTH, and calcitonin and the assessment of vitamin D status, kidney function, and blood glucose status, including hemoglobin A1c." (PMID 40740723, 2025). "Furthermore, the strongest predictors of hypocalcemia were pre-treatment levels of albumin-adjusted serum calcium (p < 0.05) and creatinine (p < 0.05)." (PMID 40149708, 2025). "Hypocalcemia was evaluated using the Common Terminology Criteria for Adverse Events (v5.0) based on the albumin-adjusted serum calcium levels; its incidence (stratified by renal function) and risk factors were investigated using a Chi-square test and logistic regression analysis." (PMID 38360579, 2024). "We chose to assume that albumin levels were normal, but this may have led to overestimation of the rates of hypocalcemia following treatment with both antiosteoporosis medications." (PMID 39416429, 2024). "Statistical analysis was performed with Statistica 13 software (StatSoft, USA).RESULTS: On the first day, hypocalcemia (low albumin-adjusted calcium level) was detected in 40.6% of cases, the prevalence of vitamin D deficiency/insufficiency amounted to 95.3% of cases." (PMID 37694870, 2023). "Therefore, correcting blood albumin concentrations is necessary to evaluate hypocalcemia using the tCa." (PMID 37885616, 2023). "On the contrary, a finding of hypocalcemia is more frequent but could be mostly related to the reduction of albumin, which is often found in cancer patients." (PMID 37568563, 2023). "As albumin-corrected calcium was used for calculations and hypocalcemia and proteinuria might introduce discordance between calcium and albumin levels, interpretation of this particular association is highly complex and exceeds the scope of this analysis." (PMID 37415042, 2023).